CDK5R1 (cyclin dependent kinase 5 regulatory subunit 1)
Description:
p35 is a neuron specific activator of CDK5. The complex p35/CDK5 is required for neurite outgrowth and cortical lamination. Involved in dendritic spine morphogenesis by mediating the EFNA1-EPHA4 signaling. Activator of TPKII. The complex p35/CDK5 participates in the regulation of the circadian clock by modulating the function of CLOCK protein: phosphorylates CLOCK at 'Thr-451' and 'Thr-461' and regulates the transcriptional activity of the CLOCK-BMAL1 heterodimer in association with altered stability and subcellular distribution.
Synonyms: p35; p25; p23; CDK5R; NCK5A; p35nck5a; CDK5P35
Tractability: Small molecule: a structure with a bound ligand is known; a high-quality ligand is known; it has a binding pocket of medium quality; it belongs to a druggable protein family. Antibody: UniProt places it where antibodies can reach, with high confidence; its Gene Ontology location is reachable by antibodies, with high confidence. PROTAC: UniProt records ubiquitination sites on it; a small molecule that binds it is known.
Target class: Kinase; Protein kinase regulatory subunit; Enzyme
Gene: Protein-coding gene on chromosome 17 (32,486,156 to 32,491,253, forward strand). Ensembl gene ENSG00000176749.
Subcellular location: Cell membrane (Cyclin-dependent kinase 5 activator 1, p35); Cell projection, neuron projection; Nucleus (Cyclin-dependent kinase 5 activator 1, p25); Cytoplasm, perinuclear region; Perikaryon
Subcellular location (Human Protein Atlas): Nucleoplasm; Vesicles
Pathways (Reactome):
Gene expression (Transcription): NPAS4 regulates expression of target genes
Signal Transduction: Activated NTRK2 signals through CDK5; NGF-stimulated transcription
Developmental Biology: CRMPs in Sema3A signaling
Disease: Deregulated CDK5 triggers multiple neurodegenerative pathways in Alzheimer's disease models
Gene Ontology:
Molecular function: cyclin-dependent protein serine/threonine kinase activator activity; protein binding; protein kinase binding; protein serine/threonine kinase activator activity; alpha-tubulin binding; beta-tubulin binding; cadherin binding; calcium ion binding; kinase activity; protein kinase activator activity; protein kinase activity; actin binding; actin filament binding; ionotropic glutamate receptor binding; protease binding
Biological process: negative regulation of DNA-templated transcription; peptidyl-serine phosphorylation; peptidyl-threonine phosphorylation; axon guidance; axonal fasciculation; brain development; ephrin receptor signaling pathway; G protein-coupled acetylcholine receptor signaling pathway; ionotropic glutamate receptor signaling pathway; microtubule cytoskeleton organization; neuron cell-cell adhesion; neuron differentiation; neuron migration; neuron projection development; positive regulation of microtubule polymerization; positive regulation of neuron apoptotic process; regulation of cyclin-dependent protein serine/threonine kinase activity; regulation of dendritic spine morphogenesis; regulation of macroautophagy; regulation of neuron differentiation; cerebral cortex radially oriented cell migration; regulation of actin cytoskeleton organization; regulation of microtubule cytoskeleton organization
Cellular component: cyclin-dependent protein kinase holoenzyme complex; nucleoplasm; nucleus; perikaryon; perinuclear region of cytoplasm; protein kinase 5 complex; axon; contractile muscle fiber; cytoplasm; cytosol; dendrite; dendritic spine; growth cone; membrane; neuromuscular junction; neuron projection; neuronal cell body; plasma membrane; postsynaptic density
Genetic constraint (gnomAD): Loss-of-function variants: 1 observed, 20.29 expected, observed/expected ratio (o/e) 0.0493, 90% interval 0.017 to 0.23. The upper end of that interval is the gene's LOEUF score, 0.23, which puts it in group 1 of 6, group 1 being the genes least tolerant of losing a copy. Missense variants: 314 observed, 421.34 expected, observed/expected ratio (o/e) 0.75, 90% interval 0.68 to 0.82. Synonymous variants: 225 observed, 199.74 expected, observed/expected ratio (o/e) 1.13, 90% interval 1.01 to 1.26.
Homologues: Orthologues: chimpanzee CDK5R1 (100% identical), guinea pig CDK5R1 (99% identical), macaque CDK5R1 (99% identical), dog CDK5R1 (99% identical), pig CDK5R1 (99% identical), mouse Cdk5r1 (98% identical), rat Cdk5r1 (96% identical), zebrafish cdk5r1b (81% identical), tropical clawed frog cdk5r1 (72% identical), zebrafish cdk5r1a (66% identical). Paralogues in human: CDK5R2 (56% identical).
Diseases named in the same sentence as CDK5R1 in open-access papers:
CDK5R1 is named in the same sentence as 39 diseases in open-access papers, as found by Europe PMC text mining. Sharing a sentence is not in itself a finding about the gene and the disease. The quoted sentences say what the papers report.
Alzheimer disease (8 papers, 2014 to 2022). A progressive, neurodegenerative disease characterized by loss of function and death of nerve cells in several areas of the brain leading to loss of cognitive function such as memory and language. "Rs13301996 is intronic to CDK5RAP2, which encodes a regulator of CDK5 activity, interacts with CDK5R1 and pericentrin (PCNT), plays a role in centriole engagement and microtubule nucleation and has been linked to primary microcephaly and Alzheimer’s disease." (PMID 34165540, 2021). "Overall, our work provides evidence of another level of CDK5R1 expression regulation mediated by long non-coding RNAs, which can also impact on Alzheimer’s disease research." (PMID 29997370, 2018). "MiR-103a-3p and miR-107 have been recently shown to target human CDK5R1, coding for the regulatory subunit 1 of cyclin-dependent kinase 5, a protein found to be hyperactivated in different neurodegenerative diseases, including Parkinson’s and Alzheimer's diseases." (PMID 25304816, 2014). "According to the Alzheimer’s disease pathway (hsa05010), we listed the main AO targets that regulate tau phosphorylation, such as MAPT, GSK3B, CDK5, CDK5R1, and CAPN1." (PMID 36533181, 2022).
cognitive disorder (4 papers, 2007 to 2023). A disease affects cognitive processes. "MiR-148a-3p decreases tau hyperphosphorylation at Ser202/Thr205, Ser199, Ser396, and Ser404 by targeting cyclin-dependent kinase 5 regulatory subunit 1 (CDK5R1) mRNA, which encodes the p35 protein, and intracerebroventricular injections of miR-148a-3p ameliorate cognitive deficits in AD model mice." (PMID 38003448, 2023). "The fine tuning of CDK5R1 expression by 3'-UTR may have a role in central nervous system development and functioning, with potential implications in neurodegenerative and cognitive disorders." (PMID 18053171, 2007).
cocaine addiction (3 papers, 2021 to 2022). "Among up- and downregulated genes from the pathway hsa05030:cocaine addiction are genes JUN, GNAS, BDFN, and CDK5R1 (upregulated), and FOSB, NFKB1, CREB1 and PPP1R1B (downregulated)." (PMID 34947877, 2021).
mental retardation (2 papers, 2007 to 2015). "CDK5R1 has been implicated in neurodegenerative disorders and proposed as a candidate gene for mental retardation." (PMID 18053171, 2007). "Disruption of the CDK5 or p35 (CDK5R1) genes induces abnormal neuronal layering in various regions of the mouse brain via impaired neuronal migration, which may be relevant for mental retardation in humans." (PMID 26469698, 2015).
non-small cell lung carcinoma (2 papers, 2021 to 2022). A group of at least three distinct histological types of lung cancer, including non-small cell squamous cell carcinoma, adenocarcinoma, and large cell carcinoma. "As there is little literature on CDK5R1, with the performance of GSEA, we only found that notch signaling pathway and non-small cell lung cancer were significantly enriched in the CDK5R1 high expression phenotype." (PMID 33346796, 2021). "GSEA disclosed that notch signaling pathway and non-small cell lung cancer were prominently enriched in CDK5R1 high expression phenotype." (PMID 33346796, 2021). "In our analysis, 2 signaling pathways that were prominently enriched in high CDK5R1 expression phenotype were filtered out, including notch signaling pathway and non-small cell lung cancer." (PMID 33346796, 2021).
prostate carcinoma (2 papers, 2017 to 2021). A carcinoma that arises from epithelial cells of the prostate gland. "CRABP2, HPD, ZEB2 and CDK5R1 are the common DEGs both in breast and prostate cancer." (PMID 33407865, 2021).
type 2 diabetes (2 papers, 2016 to 2019). "UNC119 is also located on chromosome 17, together with TSEN54 and CDK5R1, known for sight-threatening retinopathy in type 2 diabetes and disturbed retinal morphology, respectively." (PMID 30718923, 2019).
alcohol dependence (1 paper, 2026). Physical and psychological dependence on alcohol. "Epigenetic regulation was particularly evident at two methylation sites (cg07437263 and cg05102552) that indirectly influenced alcohol dependence risk by modulating CDK5R1 (63.92% mediation) and NRBP1 (95.12% mediation) expression." (PMID 42025296, 2026). "Our integrative analysis identified 10 drug-targetable genes showing significant expression alterations in alcohol dependence (FDR < 0.05), with three genes (CDK5R1, CAMKK2 and NRBP1) demonstrating evidence of shared causal variants through colocalization." (PMID 42025296, 2026). "This investigation spotlights the regulatory function of DNA methylation on CDK5R1 and NRBP1 in alcohol dependence." (PMID 42025296, 2026). "The strong mediation effects observed for CDK5R1 and NRBP1, coupled with their colocalization evidence, position these genes as promising candidates for both biomarker development and targeted therapeutic interventions in alcohol dependence." (PMID 42025296, 2026). "It implies that CDK5R1 and NRBP1 could serve as potential clinical biomarkers or therapeutic targets for the early management of alcohol dependence." (PMID 42025296, 2026).
colorectal cancer (1 paper, 2025). A primary or metastatic malignant neoplasm that affects the colon or rectum. "Moreover, CDK5R1 has been identified as a prognostic marker associated with poor survival in colorectal cancer." (PMID 40585960, 2025).
depression (1 paper, 2025). "We identified eight signature genes related to both Pueraria and depression, with MMP9, MGAM, and CDK5R1 being of particular importance." (PMID 41323994, 2025).
diabetes (1 paper, 2016). "Cdk5r1, due to its key role as a CDK regulator and the activity of the CDK5 complex in diabetes, was chosen as a potential candidate for further studies." (PMID 26788519, 2016). "Therefore, our results demonstrate that activation of the novel Cdk5: Cdk5r1 cell cycle kinase may be used as a potential therapeutic entry point for increasing β-cell mass ex vivo for islet transplantation therapy or expansion of endogenous β-cell mass in vivo as a treatment for diabetes." (PMID 26788519, 2016).
Ewing sarcoma (1 paper, 2023). A small round cell tumor that lacks morphologic, immunohistochemical, and electron microscopic evidence of neuroectodermal differentiation. "Tumors from mice xenografted with Ewing’s sarcoma cells: Control-miR, miR-152-mimic, Control-siRNA, and CDK5R1-siRNA-transfected cells, were analyzed." (PMID 37899376, 2023). "In Ewing sarcoma cells, miR-152 was down-regulated and its target, CDK5R1, was up-regulated." (PMID 37899376, 2023).
glioblastoma (1 paper, 2016). The most malignant astrocytic tumor (WHO grade IV). "At the same time, CDK5R1 is a neural specific activator of CDK5, which could regulate glioblastoma cell migration and invasion." (PMID 27153061, 2016).
medullary thyroid carcinoma (1 paper, 2023). "CDK5R1 is one of the activators of CDK5, which binds and activates CDK5 to drive G1-S transition and RB phosphorylation in medullary thyroid carcinoma models." (PMID 38093298, 2023).
Obesity (1 paper, 2021). Accumulation of substantial excess body fat. "The results revealed that 18 of the DMR genes were associated with addiction and obesity (ADCY3; ADCY9; ATF4; CDK5R1; CHRNB2; GABRD; GABRG3; GNB1; GNB3; GRK5; HDAC4; HDAC9; MAP2K1; PDE11A; PDE2A; PDE3A; PPP1CA; SLC6A3)." (PMID 34389046, 2021).
Stroke (1 paper, 2025). Sudden impairment of blood flow to a part of the brain due to occlusion or rupture of an artery to the brain. "Upregulation of ADGRL1, CDK5R1/CDKL3, CHRNB2, and ROR2 genes in post-stroke long-lasting brain fatigue generally supports neuroplasticity, cognitive recovery, and neurogenesis, which are beneficial for rehabilitation." (PMID 40006074, 2025). "The upregulation of ADGRL1, CDK5R1/CDKL3, CHRNB2, and ROR2 gene expression in the context of long-lasting post-stroke brain fatigue can have a mix of positive and negative effects, depending on how these proteins influence brain function, recovery, and energy regulation." (PMID 40006074, 2025).
tauopathy (1 paper, 2024). Neurodegenerative disorders involving deposition of abnormal tau protein isoforms (tau proteins) in neurons and glial cells in the brain. "Known tau kinases with well-documented roles in tauopathy were also predicted to have differential activity, including GSK3B, CDK5, and CDK5R1." (PMID 38895329, 2024).
triple-negative breast carcinoma (1 paper, 2023). An invasive breast carcinoma which is negative for expression of estrogen receptor (ER), progesterone receptor (PR), and human epidermal growth factor receptor 2 (HER2). "In this study, we accessed the effects of SFN on mitosis delay and cell cycle progression in the triple-negative breast cancer (TNBC) cell line MDA-MB-231 and ductal carcinoma cell line ZR-75-1 and investigated the possible underlying involvement of CDK5R1 in the achievement of these effects." (PMID 37189614, 2023).
cancer (8 papers, 2020 to 2024). A tumor composed of atypical neoplastic, often pleomorphic cells that invade other tissues. "Although accumulative studies have demonstrated the clinical significance of CDK5R1 in various cancer types, up to date, the effect of CDK5R1 on HCC has not been reported." (PMID 33346796, 2021).
neurodegenerative disease (3 papers, 2007 to 2022). A disorder of the central nervous system characterized by gradual and progressive loss of neural tissue and neurologic function. "CDK5R1 plays an important role during neurodevelopment and is associated with the development of neurodegenerative diseases." (PMID 36561735, 2022). "Thus an up-regulation of CDK5R1 expression in neurons may have pathological implications causing neurodegenerative diseases." (PMID 18053171, 2007). "Cyclin-dependent kinase 5 regulatory subunit 1 (CDK5R1) is one of the key genes in the Reelin pathway, whose activity plays an important role in neuronal differentiation and migration during neurodevelopment and is involved in neurodegenerative diseases." (PMID 36561735, 2022).
neurologic disorders (3 papers, 2017 to 2024). "It has also been proposed that CRL2FEM1B might be involved in neurologic disorders, such as Alzheimer’s, by regulating the function of cyclin-dependent kinase 5 activator 1 (CDK5R1)." (PMID 38360992, 2024). "Abnormal expression of NR3C1 in the cerebral cortex may have a relevance for neurological disorders given the predicted contribution to regulation of CDK5R1." (PMID 28720872, 2017).
tumor (3 papers, 2020 to 2023). "The high expression of CDK5R1 in HCC tissues was significantly associated with tumor status (P=0.00), new tumor event (P=0.00), clinical stage (P=0.00) and topography (P=0.00)." (PMID 33346796, 2021). "We found that overexpressed CDK5R1 was significantly associated with tumor status (OR = 2.28 for with tumor vs. tumor free, P=0.00), new tumor event (OR = 1.95 for yes vs. no, P=0.00), clinical stage (OR = 2.10 for III-IV vs. I-II, P=0.00) and topography (OR = 2.08 for T3-4 vs. T1-2, P=0.00)." (PMID 33346796, 2021). "The finding that reduced expression of CDK5R1 led to tumor shrinkage in mice is consistent with previous findings on the cell proliferative effect of CDK5R1." (PMID 37899376, 2023). "Additionally, CDK5 and CDK5R1 were overexpressed in tumor tissues of patients with metastasis." (PMID 33240752, 2020). "CDK5R1 and CCNE protein levels were significantly downregulated in tumor tissues collected from the miR-152-mimic and CDK5R1-siRNA groups." (PMID 37899376, 2023). "It was shown that the transfection with miR-152 mimic reduced the expression of CDK5R1 and CCNE in tumor tissues, even in mice." (PMID 37899376, 2023). "Significant tumor shrinkage was observed in the miR-152 mimic-CDK5R1 knockdown groups compared with the negative control groups." (PMID 37899376, 2023). "Expression of CDK5R1 and CCNE in tumor tissues was evaluated by immunostaining." (PMID 37899376, 2023).
infection (1 paper, 2025). The state of being infected such as from the introduction of a foreign agent such as serum, vaccine, antigenic substance or organism. "At 12-weeks post infection, only two AD genes Cdk5r1 and IL1a demonstrated statistically significant alteration of their expression compared with the sham-infected brain tissue." (PMID 40171450, 2025).
CDK5R1 also shares sentences with these, for which no sentence is quoted: hepatocellular carcinoma (3 papers); glioma (2); memory impairment (2); Parkinson’s (2); adenocarcinoma (1); benign tumors (1); bladder cancer (1); breast carcinoma (1); chronic myeloid leukemia (1); Huntington disease (1); lung adenocarcinoma (1); melanoma (1); oral squamous cell carcinoma (1); pancreatic cancer (1); Primary microcephaly (1); retinopathy (1).